MISO1 (mitochondrial inner membrane subdomain organizer 1)
Description:
Regulates mitochondrial morphology and mitochondrial DNA (mtDNA) homeostasis. Promotes the formation of specialized mitochondrial subdomains called small MTFP1-enriched mitochondria (SMEM). Negatively regulates mitochondrial fusion by excluding fusion coordinator OPA1 from SMEM. Recruits mtDNA, potentially through interaction with SSBP1, and facilitates mtDNA transport to the mitochondrial periphery. Also recruits other proteins, including PHB1, PHB2 and MTFP1, into SMEM which promotes peripheral mitochondrial fission, facilitating lysosome-mediated clearance of damaged mtDNA via mitophagy. [Isoform 2]: Secreted protein which may play a role in transcription regulation via the MAPK3/MAPK1 pathway through an unidentified receptor on the plasma membrane.
Synonyms: C3orf33; MISO; FLJ31139; AC3-33
Tractability: Antibody: UniProt places it where antibodies can reach, with high confidence; UniProt predicts a signal peptide or a membrane-spanning region; its Gene Ontology location is reachable by antibodies, with medium confidence.
Gene: Protein-coding gene on chromosome 3 (155,762,612 to 155,806,288, reverse strand). Ensembl gene ENSG00000174928.
Subcellular location: Mitochondrion inner membrane (Isoform 1); Secreted (Isoform 2)
Gene Ontology:
Molecular function: protein binding
Biological process: negative regulation of ERK1 and ERK2 cascade; negative regulation of mitochondrial fusion; positive regulation of mitochondrial fission
Cellular component: extracellular region; mitochondrial inner membrane; mitochondrion
Genetic constraint (gnomAD): Loss-of-function variants: 17 observed, 18.44 expected, observed/expected ratio (o/e) 0.92, 90% interval 0.63 to 1.38. The upper end of that interval is the gene's LOEUF score, 1.38, which puts it in group 5 of 6, group 1 being the genes least tolerant of losing a copy. Missense variants: 248 observed, 226.31 expected, observed/expected ratio (o/e) 1.1, 90% interval 0.99 to 1.22. Synonymous variants: 101 observed, 79.64 expected, observed/expected ratio (o/e) 1.27, 90% interval 1.08 to 1.5.
Homologues: Orthologues: macaque C2H3orf33 (94% identical), chimpanzee C3H3orf33 (94% identical), dog C3orf33 (83% identical), rabbit C3orf33 (80% identical), rat C2h3orf33 (74% identical), mouse E130311K13Rik (73% identical), guinea pig C3orf33 (67% identical), zebrafish C18H3orf33 (35% identical), Caenorhabditis elegans F32A11.1 (27% identical).
Diseases named in the same sentence as MISO1 in open-access papers:
MISO1 is named in the same sentence as 2 diseases in open-access papers, as found by Europe PMC text mining. Sharing a sentence is not in itself a finding about the gene and the disease.
MISO1 shares sentences with these, for which no sentence is quoted: cancer (2 papers); colorectal cancer (1).